PTX3 (pentraxin 3)
Diseases named in the same sentence as PTX3 in open-access papers (continued):
Sharing a sentence is not in itself a finding about the gene and the disease.
infection (continued). "We studied plasma pentraxin 3 (PTX3) upon admission to the emergency department in patients with suspected infection." (PMID 23341967, 2013). "mDCs themselves also secrete PTX3 upon exposure to viral particles and maintains the loop of infection followed by immuno-protection." (PMID 23755050, 2013). "The present findings confirm previous results on PTX3 in detecting severe disease, and show that PTX3 can be used in patients with suspected infection on admission." (PMID 23341967, 2013). "In healthy persons the PTX3 concentration has been shown to be lower than 2 ng/ml, while PTX3 levels increase rapidly in response to inflammation and infection." (PMID 23341967, 2013). "The regulated expression of this molecule in macrophages and dendritic cells suggests that PTX3 represents a mechanism of amplification of innate resistance against pathogens mainly acting locally at the site of infection and inflammation." (PMID 23401658, 2013). "In critically ill ICU-patients the levels of PTX3 have correlated with the severity of disease and infection." (PMID 23341967, 2013). "We showed here that high levels of PTX3 in plasma as well as high levels of PCT can be used as prognostic markers in patients with suspected infection admitted to the emergency room." (PMID 23341967, 2013). "Since cytomegalovirus (CMV) infections can also result in such an immuno-compromised state, PTX3 can resolve super infection by A. fumigatus even in a CMV-infected state." (PMID 23755050, 2013). "Pentraxin 3 has been identified as biomarker of several immunopathological states and its relevance with the resolution of infections and diseases has also been studied." (PMID 23755050, 2013). "Plasma pentraxin 3 (PTX3) in patients admitted to emergency room with suspected infection stratified by diagnosis groups (N = 537)." (PMID 23341967, 2013). "PTX3 also activates the lectin complement pathway by binding to ficolin-L-bound Aspergillus conidia in an attempt to clear the infection." (PMID 23755050, 2013). "Several disease and infection models have been extremely useful in understanding the role of PTX3 in normal and immuno-compromised disease states." (PMID 23755050, 2013). "PTX3 is rapidly induced following InfV infection and therapeutic treatment of mice with human PTX3 promotes survival and reduces InfV load." (PMID 23251423, 2012). "Administration of exogenous PTX3 in early infection is able to rescue antifungal resistance and, at the same time, to restrain the exaggerated inflammatory response to the fungus by way of curbing the IL-23/Th17 inflammatory axis." (PMID 22577258, 2012). "The long pentraxin PTX3 is a prototypic soluble PRM that is produced at sites of infection and inflammation by both somatic and immune cells." (PMID 23316195, 2012). "PTX3 plasma levels are very low in normal circumstances (≤2ng/ml) but expression has been shown to increase following pathogen infection." (PMID 23046560, 2012). "In the protection afforded against infection, PTX3 recognizes certain fungi, bacteria, microbial moieties, and viruses." (PMID 23248627, 2012). "PTX3 also promotes ficolin-2-induced complement deposition on the surface of A. fumigatus, thus aiding the host to combat the infection." (PMID 22577258, 2012). "In our study, Ptx3 was induced up to 119-fold in peritoneal macrophages of B6 mice after SS2 infection, while the fold change of Ptx3 was 34.9 in SS2-infected A/J mice." (PMID 22384161, 2012). "The long pentraxin PTX3 has been shown to bind to A. fumigatus and to be critical against infection in mice models." (PMID 22666482, 2012). "PTX3-knockout and transgenic mice studies have indicated that the predominant role of PTX3 occurs in host protection in the case of lung injury, infection, vascular damage, as well as certain other disorders." (PMID 23248627, 2012). "The prognostic value of PTX3 as evaluated by ROC curve was better than that for CRP during the first days after diagnosis of bacteremic infection." (PMID 21423699, 2011).
infection (continued). "The study involved patients with non-severe disease and those admitted to the ICU due to severe infection, which enables study of the value of PTX3 in patients with distinct outcomes." (PMID 21423699, 2011). "PTX3 is an ancient and conserved pattern recognition molecule of the innate immune system that is important in protection against certain infections." (PMID 21915248, 2011). "The expression and release of PTX3 are enhanced upon inflammation and infection, leading to significantly increased PTX3 plasma levels (200–800 ng/ml versus <2 ng/ml in normal plasma) under these conditions." (PMID 21915248, 2011). "Foot ulcers are often complicated by infections, and PTX3’s role in immune response and tissue repair may make it useful in predicting wound healing and inflammation." (PMID 40299501, 2025). "Oral administration of Ptx3 has been shown to protect neonatal mice from Pseudomonas aeruginosa pulmonary infection, highlighting its vital role in protecting newborns with immature immune systems from infections." (PMID 41479916, 2025). "PTX3 is an acute‐phase reactant protein that plays a critical role in inflammatory processes and immune system modulation, rapidly produced in response to infection, injury, or inflammatory stimuli." (PMID 39853806, 2025). "Elevated PTX3 levels might correlate with infection severity and wound chronicity, providing insight into the progression of diabetic foot complications." (PMID 40299501, 2025). "Over the past few decades, PTX3, a key member of the pentraxin superfamily, has taken center stage, with accumulating evidence illuminating its versatile roles in innate immunity, inflammation, infection, tissue repair, female fertility, and cancer." (PMID 41479916, 2025). "As opposed to the polymorphisms in PTX3, the rs3024491 in IL-10 and rs2853550 in IL-1β were strongly associated with the infection status." (PMID 38790226, 2024). "Besides its roles in innate immunity to infections, PTX3 has been reported to modulate sterile inflammation in preclinical models of myocardial infarction, intestinal ischemia, and acute lung injury." (PMID 39348530, 2024). "PTX3 is rapidly produced as a homo-octameric glycoprotein by immune and stromal cells, most prominently macrophages and ECs, in response to pro-inflammatory signals and infection." (PMID 39640269, 2024). "Moreover, we determined that PTX3-regulated macrophage polarization in response to LPS infection was dependent on the NF-κB pathway." (PMID 39666228, 2024). "PTX3 is a mediator of acute inflammation and innate immunity; in chickens, it is upregulated in tissues upon stimulation with lipopolysaccharide and experimental infection with E. coli." (PMID 38254345, 2024). "Given that CPS2 was required for triggering the host’s inflammatory response during SS2 infection, we speculated that the injections of CPS2 extraction at different doses may cause the death of mice co-treated with 20 μg PTX3 at different rates." (PMID 36977278, 2023). "The PTX3 is an anti-inflammatory and anti-infection protein that activates immune cells." (PMID 38052851, 2023). "In order to define the relevance of PTX3 in pneumococcal respiratory disease, we first investigated whether the protein is induced during infection." (PMID 37222419, 2023). "Therefore, PTX3, at the interface between infection immunity and bone biology, stands out as an ideal candidate for investigations into new biomarkers of PJI." (PMID 36769703, 2023). "Produced by various cells involved in the local inflammatory response and local defense against infections, pentraxin-3 might be a better biomarker for IDFU than other systemic markers." (PMID 37510110, 2023). "This points to PTX3 being a useful marker to confirm a suspected infection." (PMID 36769703, 2023). "Interestingly, local and systemic production of PTX3 was strongly induced by the infection during the disseminating phase." (PMID 37222419, 2023).
infection (continued). "Bacterial load in lungs (E) and spleens (F) collected 36 hr post-infection from WT and Ptx3−/− mice treated intravenously 12 hr post-infection with 50 μg/100 μl of anti-CD62P or isotype control antibodies (data pooled from two independent experiments, n = 12–13)." (PMID 37222419, 2023). "Ptx3−/− mice infected by serotype 1 presented a higher sensitivity to the infection compared to WT animals, with a higher number of bacteria at the local site of infection and also in the spleen 24 hr post-infection." (PMID 37222419, 2023). "The long pentraxin PTX3 is a component of the innate immune system involved in infection immunity." (PMID 36769703, 2023). "At 18 hr post-infection, even though there was a higher amount of neutrophils in the airways of Ptx3−/− mice, we did not detect any differences in the levels of CXCL1 and CXCL2 between Ptx3-deficient and WT mice." (PMID 37222419, 2023). "In addition, defective PTX3 production after intranasal infection with S. pneumoniae was observed in Il1r−/− mice, as well as in Myd88−/− animals." (PMID 37222419, 2023). "Bacterial load in lung (A) and spleen (B) collected 36 hr post-infection from WT and Ptx3−/− mice treated intraperitoneally 12 hr post-infection with 200 μg/100 μl of anti-Ly6G or isotype control antibodies (data pooled from three independent experiments, n = 26–37)." (PMID 37222419, 2023). "The results of IL-6 levels showed that knockdown of PTX3 almost completely abolished the activation of the inflammatory response induced by the HA9801 infection, compared with the cells transfected with the non-specific siRNA (SiNC) and incubated with the PBS control." (PMID 36977278, 2023). "Moreover, we treated WT and Ptx3-deficient mice with anti-CD62P, to block P-selectin-dependent neutrophil transmigration during the invasive phase of infection." (PMID 37222419, 2023). "Adequate treatment of the infection reduces the concentration of Ptx3." (PMID 36422015, 2022). "The main characteristics of PTX3 are the local production at the site of infection or tissue damage by multiple cell types, and the consequent prompt increase of its circulating levels in inflammatory or infectious conditions, which make this molecule a candidate prognostic biomarker." (PMID 36389697, 2022). "The rapid decrease of PTX3 on POD 2 could be a positive prognostic factor for an uneventful postoperative course in terms of infection." (PMID 35989325, 2022). "Thus, this study emphasizes the relevance of the role of PTX3 as orchestrator of inflammation and tissue repair in innate responses to infections." (PMID 34093560, 2021). "In conclusion, serum PTX3 is an important and specific biomarker of early infection." (PMID 34307663, 2021). "CRP, ER, MCP-1 and PTX3 are commonly used indicators of patient infection." (PMID 34447637, 2021). "It is already elevated in the umbilical cord, so measuring PTX3 concentration might be useful in the early prediction of infection in newborns." (PMID 34307663, 2021). "Thus, this study emphasizes the relevance of the role of PTX3 as regulator of inflammation and orchestrator of tissue repair in innate responses to infections." (PMID 34093560, 2021). "Serum PTX3 is an important and specific biomarker of early infection." (PMID 34307663, 2021). "Pentraxin-3 is an acute-phase reactant involved in the processes of inflammation and infection." (PMID 34001041, 2021). "However, pentraxin-3 has been reported to protect against severe infections and be a central player in the immune and inflammatory responses." (PMID 35387000, 2021). "It is already elevated in the umbilical cord, so measuring serum PTX3 might be useful in the prediction of infection in newborns." (PMID 34307663, 2021). "However, an enhanced upregulation of 9 genes, all involved in the NF-kB pathway (CCL2/MCP1, CCL20, CCL4, CXCL2/MIP2α, IL1A, NFKBIA, PTX3, TNFA, TNFAIP3), was observed after infection with D26 variants, in comparison to the WT." (PMID 33399033, 2021).
infection (continued). "PTX3 was previously shown to be involved in innate resistance to specific infections by opsonizing microorganisms (e.g. A. fumigatus conidia and Pseudomonas aeruginosa), directly or through ficolins and collectins, and promoting complement-dependent phagocytosis." (PMID 34093560, 2021). "In infected lungs, PTX3 localized in proximity of PDGFRα+ mesenchymal cells, further supporting its role in this infection is associated with tissue remodeling and not in pro-phagocytic activity." (PMID 34093560, 2021). "Pentraxin 3 value in the umbilical cord of 3969.1 pg/mL was established as a cutoff value with 58.3% (95% CI 33.6-77.9) sensitivity and 78.4% (95% CI 61.8-90.2) specificity in prediction of infection in the first 12 hours of life." (PMID 34307663, 2021). "The serum PTX-3 levels dramatically increase within 6–8 h of infection and inflammation." (PMID 32670996, 2020). "PTX3 increases within 6–8 h of response to infection, compared to 24–30 h for CRP." (PMID 33301518, 2020). "We thereby aimed to assess if PTX3 is an appropriate marker of subclinical disease and whether its expression would correlate with the severity of infection." (PMID 30774632, 2019). "PTX3 deglycosylation in this case hence exacerbates infection." (PMID 30774632, 2019). "A search for PTX3 reads in various publicly available RNA-seq data sets of chicken spleen and bursa of Fabricius also showed that PTX3 expression increases within days after experimental infection with viral and bacterial pathogens." (PMID 30774632, 2019). "FCN1 may also interact with C-reactive protein (CRP) via a conformational change induced by mild acidosis at the local site of infection, and with pentraxin 3 (PTX3) in a Ca2+-dependent manner." (PMID 31694344, 2019). "The role of PTX3 in the innate immune system, where it acts as a pattern recognition molecule and potent complement activator, and the rapid change of its expression in the course of the acute phase of infections have been studied intensely in mice and men." (PMID 30774632, 2019). "Data collected over the years demonstrated that circulating PTX3 levels increase rapidly in response to infections and play important regulatory roles on inflammation, regulating complement activation, cell extravasation and pathogen recognition by myeloid cells." (PMID 31031772, 2019). "In addition PTX3 administration is protective also against infections with Influenza virus, murine cytomegalovirus, Neisseria meningitidis, and P. aeruginosa in neonates and during chronic infections." (PMID 31031772, 2019). "PTX3 opsonization with only the concentration of 50 μg/mL significantly decreased the number of intracellular bacteria at 1 h and 2 h post-infection (p.i.)(p< 0.001: PTX3-opsonized M90T vs. M90T plus BSA at 2h) to levels like those induced by the anti-IpaD antibody." (PMID 30532257, 2018). "As macrophages are a further source of PTX3 during infections, we analyzed whether Shigella could promote PTX3 release in macrophages, as shown in DCs." (PMID 30532257, 2018). "In line with these issues, we investigated whether treating mice with recombinant PTX3 could affect the outcome of intranasal infection with M90T, as shown with the other pathogens as above." (PMID 30532257, 2018). "We suggest that PTX3 could potentially contribute to the eradication of the infection by targeting the poorly explored extracellular phase of the invasion process, which can be considered the “Achille heels” of Shigella invasion process." (PMID 30532257, 2018). "We therefore passed to analyze a possible contribution of PTX3 in vivo, during infection." (PMID 30532257, 2018). "At 48 h of infection, the expression of c1qa and ptx3 was significantly induced in WT animals." (PMID 27100179, 2016). "This study indicates that clinicians may consider PTX3 as a marker of infection on equal terms with PCT and that these markers are more reliable as prognostic markers of disease severity than is CRP in patients with NSTI." (PMID 26880104, 2016).
infection (continued). "In addition to its wide use as a marker of inflammation and infection, PTX3 has been observed at increased levels in several cancers." (PMID 26124179, 2015). "PTX3 is a pattern recognition molecule that interacts with viruses such as murine cytomegalovirus and influenza virus, through which it can act to inhibit infection of target cells." (PMID 25695775, 2015). "In contrast, removal of the N-terminal led to a complete ablation of PTX3-enhanced infection." (PMID 25695775, 2015). "Similarly, RRV infection of HeLa cells, which are highly permissive to RRV infection and express endogenous PTX3, demonstrated clear evidence of PTX3 colocalization with RRV in the cytoplasm during infection." (PMID 25695775, 2015). "In addition PTX3 has a therapeutic potential in models of experimental infection with A. fumigatus and P. Aeruginosa." (PMID 25786110, 2015). "In our population, we found a high prevalence of cells in BAL fluid that stained positive for intracellular PTX3 by anti-hPTX3 rabbit antibodies, which may be the result of new recruitment of fresh leukocytes in response to the infection." (PMID 25314919, 2014). "In critically ill patients PTX3 correlated with severity of disease and infection." (PMID 23341967, 2013). "Since TNF induces PTX3 expression, one explanation for reduced production of TNF in this infection model could be a feedback mechanism to regulate PTX3 levels and exacerbations that may result from its very high levels." (PMID 23755050, 2013). "However, the action of PTX3 is not limited to the innate immune system: PTX3 coordinates with adaptive immune system and facilitates protection against infections." (PMID 23755050, 2013). "PTX3 binds to cytomegalovirus and influenza virus type A for the inhibition of infection." (PMID 23248627, 2012). "In vivo studies with Ptx3-deficient mice showed that PTX3 plays non-redundant roles in innate resistance to infections caused by these microorganisms, and for some of them the protective role of PTX3 is mediated by complement." (PMID 23316195, 2012). "PTX3 co-operation with the adaptive immune system in defense inflammation which combats infection supports, in its turn, development of a protective Th1/Treg immune response while at the same time it limits harmful inflammation elicited by the Th17/Th2 immune response." (PMID 22577258, 2012). "By (i) shifting the balance of these antagonistic mediators in one or another way and (ii) depending upon the inaugural inflammatory response which must deal either with a high or a low bacterial inoculum, PTX3 will either favor or disfavor the ability of the host to combat the infection." (PMID 22577258, 2012). "In critically ill patients PTX3 correlates with severity of disease and infection." (PMID 21423699, 2011). "However, the site of action for the two proteins is likely different: while CRP acts in a systemic manner as an acute phase protein, PTX3 is more likely to act locally upon infection or inflammatory stimuli, e.g. on injured endothelium." (PMID 21915248, 2011). "Furthermore, PTX3 is elevated in critically ill patients and in febrile patients admitted to the emergency room, correlating with severity of disease and infection in these patient groups." (PMID 21423699, 2011). "Serum PTX3 behaves as an acute-phase response protein, because its levels are low in normal conditions (about 25 ng/ml in the mouse) and increase moderately to dramatically upon inflammation and infection, depending on the type of stimulus." (PMID 20920344, 2010). "PTX3 is, in contrast with the hepatically derived short pentraxins, mainly produced by inflammatory cells and endothelial cells, which allows it to act locally at sites of infection and inflammation." (PMID 20920344, 2010).